TUBGCP3 (tubulin gamma complex component 3)
Description:
Component of the gamma-tubulin ring complex (gTuRC) which mediates microtubule nucleation. The gTuRC regulates the minus-end nucleation of alpha-beta tubulin heterodimers that grow into microtubule protafilaments, a critical step in centrosome duplication and spindle formation.
Synonyms: GCP3; Spc98p; SPBC98; 104p; ALP6; Grip104; Spc98
Tractability: Small molecule: a structure with a bound ligand is known. PROTAC: ubiquitination databases record sites on it; its protein half-life has been measured.
Gene: Protein-coding gene on chromosome 13 (112,485,005 to 112,588,205, reverse strand). Ensembl gene ENSG00000126216.
Subcellular location: Cytoplasm, cytoskeleton, microtubule organizing center, centrosome
Pathways (Reactome):
Cell Cycle: Recruitment of NuMA to mitotic centrosomes; Recruitment of mitotic centrosome proteins and complexes
Gene Ontology:
Molecular function: gamma-tubulin binding; protein binding; microtubule minus-end binding; structural constituent of cytoskeleton; structural molecule activity
Biological process: meiotic cell cycle; microtubule nucleation; mitotic cell cycle; single fertilization; spindle assembly; microtubule cytoskeleton organization
Cellular component: centriole; centrosome; cytoplasm; membrane; polar microtubule; cytosol; gamma-tubulin complex; spindle; microtubule organizing center; spindle pole
Genetic constraint (gnomAD): Loss-of-function variants: 42 observed, 106.07 expected, observed/expected ratio (o/e) 0.4, 90% interval 0.31 to 0.51. The upper end of that interval is the gene's LOEUF score, 0.51, which puts it in group 2 of 6, group 1 being the genes least tolerant of losing a copy. Missense variants: 820 observed, 1,058.5 expected, observed/expected ratio (o/e) 0.77, 90% interval 0.73 to 0.82. Synonymous variants: 379 observed, 396.9 expected, observed/expected ratio (o/e) 0.95, 90% interval 0.88 to 1.04.
Homologues: Orthologues: chimpanzee TUBGCP3 (99% identical), macaque TUBGCP3 (99% identical), chimpanzee TUBGCP3 (95% identical), mouse Tubgcp3 (93% identical), guinea pig TUBGCP3 (93% identical), rat Tubgcp3 (93% identical), pig TUBGCP3 (91% identical), rabbit TUBGCP3 (89% identical), tropical clawed frog tubgcp3 (87% identical), dog TUBGCP3 (83% identical), zebrafish tubgcp3 (79% identical), Drosophila melanogaster Grip91 (18% identical), and 1 more. Paralogues in human: TUBGCP2 (25% identical), TUBGCP6 (22% identical), TUBGCP5 (17% identical), TUBGCP4 (13% identical).
Diseases named in the same sentence as TUBGCP3 in open-access papers:
TUBGCP3 is named in the same sentence as 5 diseases in open-access papers, as found by Europe PMC text mining. Sharing a sentence is not in itself a finding about the gene and the disease. The quoted sentences say what the papers report.
glioma (1 paper, 2025). A benign or malignant brain and spinal cord tumor that arises from glial cells (astrocytes, oligodendrocytes, ependymal cells). "Moreover, it has been shown that TUBGCP2 and TUBGCP3 are overexpressed in glioma." (PMID 40073758, 2025).
TUBGCP3 also shares sentences with these, for which no sentence is quoted: glioblastoma (2 papers); microcephaly (1); osteoporosis (1); Wilms tumor (1).